BCL2 (BCL2 apoptosis regulator)
Diseases named in the same sentence as BCL2 in open-access papers (continued):
Sharing a sentence is not in itself a finding about the gene and the disease.
tumor (continued). "A study that sequentially delivered doxorubicin and Bcl-2-targeting siRNAs by respectively encapsulating each agent in tumor-homing nanoparticles found that the sequential treatments significantly achieved optimal efficacy in PC3-tumor-bearing mice." (PMID 36365147, 2022). "Most identified lncRNA modulates TRAIL-mediated apoptosis by either promoting or suppressing the expression of Bcl-2 which then brings about intense tumor growth, enhanced metastatic ability and chemoresistance." (PMID 36076273, 2022). "On the other hand, an additional target of miR-184, programmed cell death 4 (PDCD4), has been described to be a tumor suppressor by acting at the level of c-Myc and Bcl-2, inhibiting the cell proliferation and survival in nasopharyngeal cancer cells." (PMID 35883677, 2022). "Bax and Bcl-2 protein expression involvement is critical in determining tumor responsiveness to a specific anticancer treatment." (PMID 36139697, 2022). "The resulting data indicated that TLR4, MyD88, NF‐κB p65, and Bcl‐2 protein levels were markedly increased and Bax levels reduced after P. copri treatment compared with the tumour control group." (PMID 35735103, 2022). "BCL2 family members, including Bcl-2, Bcl-XL, and Mcl-1, promote cell survival by binding to and sequestering proteins that promote apoptosis in tumor cells." (PMID 35681786, 2022). "Our results indicated that tumor tissues of mice exposed to BDMC showed relatively lower levels of anti-apoptotic proteins (Bcl-2) and XIAP when compared to the control group." (PMID 35008959, 2022). "Rituximab-mediated downregulation of IL10 suppresses BCL2 expression and enhances apoptosis in tumour cells." (PMID 36090032, 2022). "Western blotting analysis revealed significantly increased IGF2BP3, p-PI3K, p-AKT and BCL2 expression in AB+-treated tumor tissues." (PMID 35615150, 2022). "ω-6 PUFAs rely on the catalytic effect of COX-2 to generate PGE2 in the body, which can stimulate the expression of Bcl-2 protein to imbalance cell proliferation and apoptosis and thus promote tumor progression." (PMID 35251974, 2022). "Mechanistic study revealed that nuciferine enhanced apoptosis of tumor cells, upregulated the expression of Bax and Axin, and downregulated the expression of Bcl-2 and β-catenin." (PMID 35158798, 2022). "This is the ideal location for ppp-BCL2 dsRNA delivery because it simultaneously acts as a RIG-I agonist inducing pro-CTL Th1-skewing (e.g., IFNα/β) cytokines and silences the anti-apoptotic BCL2 gene, making the tumor more vulnerable to the immune response." (PMID 35154473, 2022). "Indirect associations are noted between the NFκB, FAK, PI3K/AKT, WNT-β-catenin, BCL2, and tumor microenvironment pathways." (PMID 36009530, 2022). "The lncRNA MALAT1 was highly expressed in NSCLC cell exosomes and tissues, and its knockdown induced apoptosis by regulating Bcl-2/Bax protein expression and exerted anti-tumour effects by targeting EEF2 via miR-515-5p." (PMID 35379783, 2022). "In BC cells, estrogen promotes tumor progression by inhibiting apoptosis through upregulated anti-apoptotic Bcl-2 and Bcl-X L and activation of MAPK and PI3K/Akt pathways." (PMID 35847988, 2022). "The released DOX presented inefficient inhibition of the tumor progression, owing to the upregulation of Bcl-2 expression induced decreased apoptosis of tumor cells." (PMID 36297356, 2022). "The advantages that NKExos provide in terms of tumor specificity, cell uptake and siRNA release make them a promising delivery option for Bcl-2 targeting." (PMID 35056993, 2022). "Shikonin induces apoptosis of tumor cells by affecting the expression of pro-apoptotic protein Bax and inhibiting the expression of anti-apoptotic protein (bcl-2, Bcl-x, etc.)in the Bcl-2 gene family." (PMID 35873044, 2022). "As a result, the application of X-ray radiation (1 Gy) alone resulted in facilitated expression of Bax and Caspase-3 and declined expression of bcl-2 in the tumor cells." (PMID 34968160, 2022).
tumor (continued). "Many other studies have also reported Bax and Bcl-2 to be crucial factors for modulating tumour response when using drug-loaded MB combined with ultrasound." (PMID 35457210, 2022). "The aim of this study was to assess the expression of anti-apoptotic Bcl-2 and pro-apoptotic Bax in the epithelium as well as the lamina propria of normal colonic controls, low-grade tumor samples and high-grade tumor samples." (PMID 36013602, 2022). "In a study of low-grade EC treated with progestin, Bcl-2 was downregulated, concomitant with tumor cell maturation and reduced Ki-67 staining." (PMID 36551694, 2022). "Inhibition of STAT-3 in tumor cells leads to down-regulation of its transcriptional targets belonging to the Bcl-2 family including the antiapoptotic Bcl-2, Bcl-XL and Mcl-1." (PMID 35203723, 2022). "miR-148a deactivates the intrinsic mitochondrial pathway via Bcl-2 inhibition and tumor apoptosis induction in CRC." (PMID 35997665, 2022). "Bcl-2 has an anti-apoptotic protagonist, causing unfortunate clinical consequences or resistance to therapy in most tumor types expressing Bcl-2." (PMID 36299777, 2022). "Venetoclax stimulated BIM-dependent cell death in vitro, inhibited cancer growth, and stimulated tumor failures in mice bearing more Bcl-2–expressing SCLC cancers in vivo." (PMID 35402265, 2022). "Many studies have shown that BCL-2 exerts its tumor-promoting function through cooperation with anti-apoptotic proteins and inhibition of pro-apoptotic proteins." (PMID 35193595, 2022). "The combination of the upregulation of ROS by activated Src/Ras signaling and of Bcl-2 by PKC accounts for Cr(VI)-mediated tumor promotion." (PMID 35210368, 2022). "EF24 is also an anti-tumor agent that can kill melanoma cells effectively via downregulating the expression of Bcl-2 and IAP by inhibiting the NF-κB signaling." (PMID 35252191, 2022). "PKC-α is highly expressed in rat hepatoma cells, and treatment with Pkc-α-ASO reduces the expression of anti-apoptotic protein Bcl-2, promotes cell apoptosis, and inhibits the growth of tumor cells." (PMID 36569303, 2022). "Just as the anti-apoptotic Bcl-2 proteins promote tumourigenesis when deregulated, the pro-apoptotic members function as tumor suppressors." (PMID 35207544, 2022). "By contrast, an increase in BIM and PTEN led to changes in BIM/Bcl-2 and PTEN/AURKA and, consequently, caused apoptosis which inhibited tumor growth." (PMID 36678556, 2022). "Further results on Bax/Bcl-2 coincided with the reduction in tumor growth as indicated by the Ki67 staining." (PMID 35959493, 2022). "Expression of BCL2 was shown to be highly upregulated in many cancers as compared to normal tissue, suggesting its tumor promoting role." (PMID 35955749, 2022). "The downregulation of Bcl-2 after C-PC treatment was also confirmed by another in vitro study with AK-5 tumor cells." (PMID 35567250, 2022). "It has been shown that Mcl-1 upregulation can render several tumor cells resistant to the Bcl-2/Bcl-xL inhibitors ABT-737 and ABT-263." (PMID 36104717, 2022). "Given the reduced Bcl-2 protein and increased expression of Puma in bcl-3−/− tumors, Bcl-3 likely contributes to tumor cell survival, in part, through the activation and repression of these genes, respectively." (PMID 35681213, 2022). "Further, our preclinical studies presented tumor growth inhibition in athymic mice presumably due to selective inhibition of BCL-2." (PMID 36358660, 2022). "Studies have revealed that geraniin exerts significant inhibitory effects on tumor growth and markedly promotes cancer cell apoptosis by increasing the expression of Bax, caspase-3, and caspase-9 and decreasing the level of Bcl-2." (PMID 35222793, 2022).
tumor (continued). "Activation of antiapoptotic Bcl-2 family proteins, such as Bcl-2, Mcl-1, and Bcl-xL, are frequently observed in chemoresistant tumor cells, offsetting the functions of proapoptotic Bcl-2 family proteins and suppressing apoptosis." (PMID 36430955, 2022). "For example, BCL2 family are central regulators of apoptosis, and up-regulation of BCL2 has been shown to lead to tumor development and progression as well as resistance to cancer therapy." (PMID 36685857, 2022). "In the analysis of the relative expression level of the tested long non-coding RNA H19, MALAT1 and gene BCL2 we obtained statistically significant levels when comparing tumor versus normal adjacent samples." (PMID 35723379, 2022). "Bcl-2 participates in a fundamental function in cancer growth, angiogenesis, and tumor vascular density." (PMID 35402265, 2022). "As we all know, Bax, Bcl-2, and cleaved caspase-3 proteins play an important role in the apoptosis of tumor cells, and their abnormal expression is critical to the occurrence and development of cancer." (PMID 36159567, 2022). "Treatment of Annonacin (0.5–1 μM) induced MCF breast cancer cell line death at 48 h and treatment of Annonacin (0.1 μM) in xenografts tumor decreases the expression of ER, cyclin D1, and Bcl2." (PMID 36139697, 2022). "Venetoclax is a selective inhibitor of the broad-spectrum anti-apoptotic protein BCL2 and has shown cytotoxic activity in BCL2-overexpressing tumor cells." (PMID 35335935, 2022). "In this study, in the form of a drug delivery formulation, synthetic miR-204 was again confirmed to be able to inhibit tumor growth in vitro and in vivo, and the expressions of BCL2 and RAB22A were significantly down-regulated in tumor tissue." (PMID 36231028, 2022). "Venetoclax is an oral BH3-mimetic drug designed to inhibit the function of the Bcl-2 protein, thus, inducing apoptosis in tumor cells." (PMID 35456167, 2022). "APG-2575 is a novel BCL-2 selective inhibitor, which has demonstrated anti-tumor activity in hematologic malignancies." (PMID 35794605, 2022). "AGS-H synergistic with CTX significantly inhibited the expression of Bcl-2 and promoted Bax and cleaved-Caspase-3 in tumor tissues (P < 0.05, P < 0.001)." (PMID 35445056, 2022). "The results of the present study implied that CO-PNs generated oxidative stress in MCF-7 cells by upregulating the expression of the pro-apoptotic gene Bax and down-regulating of Bcl-2 by tumor suppression and pro-apoptosis genes." (PMID 36234520, 2022). "Evidence demonstrated that sca RNA2 induces tumor proliferation by promoting the expression of Bcl-2 and EGFR." (PMID 36076273, 2022). "Cancer cells have developed various strategies to limit or evade apoptosis by upregulating anti-apoptotic components (e.g., Bcl-2, Bcl-xL, and Mcl-1) or decreasing the tumor-suppressive function of proapoptotic factors (e.g., Bax)." (PMID 35898889, 2022). "Later, the tumor-suppressing mechanism of these miRNAs in CLL was identified via the Bcl2 gene, which codes for the antiapoptotic protein B." (PMID 36232799, 2022). "In both models, isoliensinine showed reduced tumor growth through the apoptosis of tumor cells mediated by increased caspase-3 activity, decreased levels of Bcl-2, Bcl-xL, and MMP-9, and decreased NF-κB p65 phosphorylation." (PMID 35158798, 2022). "The balance between Bax and Bcl-2 proteins can be seen by evaluating the sensitivity of tumor cells to GCV." (PMID 35795095, 2022). "Together, these data illustrate the importance of mediated Ca2+ flux by Bcl2 in T cell differentiation, longevity, and tumor control." (PMID 35573704, 2022). "After the initial NACT, the downregulated mir-141 was associated with positive regulation of several suggested tumor suppressors, such as IRF6, BCL2, KLHL20." (PMID 35200555, 2022). "After JNK is activated, Bcl-2 becomes phosphorylated, and that destroys the interaction between BECN1 and Bcl-2 and induces the autophagy of tumor cells." (PMID 35269473, 2022).
tumor (continued). "Both Bcl-2 apoptosis regulator (Bcl-2) and X-linked inhibitor of apoptosis protein (XIAP) were recognized as anti-apoptosis factors that contribute to tumor progression, while Bcl-2-associated X (BAX) and caspase-3 were known as apoptosis markers." (PMID 35008959, 2022). "It has also been suggested that IL-6, IL-22, and IL-10 can influence tumor drug resistance by regulating apoptosis-related proteins like BCL-2 and IAPs." (PMID 36245983, 2022). "In 54% of patients BCL-2 was expressed in the tumor cells, while BCL-XL and BCL-W were expressed in 88 and 90% and MCL1 in 78%." (PMID 36430230, 2022). "Through the unfolded protein response (UPR), the B cell lymphoma 2 (BCL-2) protein family, the Caspase signaling pathway, and others, ER-phagy plays an initiating role in tumor occurrence, migration, stemness, and proliferation." (PMID 35327508, 2022). "In many drug-resistant tumor cells, the increase of anti-apoptosis protein Bcl-2 and the decrease of pro-apoptotic protein Bax have been observed." (PMID 36157053, 2022). "In this study, the mechanism of ATL-1 regulating Bcl-2/Bax signaling pathway on tumor cells was investigated." (PMID 36686743, 2022). "In contrast, HCC group showed an increase in Bcl-2-expressing liver cells reaching its peak 40 days from the onset of tumor formation." (PMID 33773560, 2021). "Hsa_circ_0003970 and hsa_circ_0005848 interacted with miRNA-204-5p, which is a tumor suppressor that promotes apoptosis by targeting BCL2 in PCa cells." (PMID 33574834, 2021). "Results from in vitro studies indicate that STAT3 inhibition increases the Bax/Bcl-2 ratio leading to apoptosis of tumor cells." (PMID 33807148, 2021). "The expression of Beclin-1 and Bcl-2 was evaluated in both tumor tissues and adjacent tissues using IHC." (PMID 34257544, 2021). "With tumor sphere-formation in CD133+/ CD44+ MiaPaCa2 cells, loss of miR-34 and increase of Notch/Bcl-2 has been reported." (PMID 34094034, 2021). "On the contrary, the inhibition of the anti-apoptotic protein BCL-2 has been shown to increase tumor responsiveness to doxorubicin in TNBC." (PMID 34833068, 2021). "STAT proteins inhibit tumor cell apoptosis and promote cell proliferation by increasing the levels of anti-apoptotic proteins (BCL-2, BCL-xl." (PMID 34090412, 2021). "Mechanistic investigations demonstrated that the miR-197-mediated CKS1B/STAT3 axis was excavated exerting tumor progression regulated by various protooncogenes like BCL2 Apoptosis Regulator (BCL2), MYC, and Cyclin D1(CCND1)." (PMID 34925510, 2021). "Tumor cells become apoptosis defects via upregulating expression of antiapoptotic proteins like Bcl-2 or via downregulating levels of proapoptotic proteins such as Bax." (PMID 33986660, 2021). "Bcl-2 overexpression has also been reported in about 50% of GBM patients, which was associated with a significant enhancement of tumor resistance against adjuvant therapies." (PMID 34070493, 2021). "It was demonstrated that the combination of CXCL12 with CXCR4 and CXCR7 on tumor cells leads to antiapoptotic signals upregulated by Bcl‐2 and survivin, and affects the progression of gastrointestinal tumors." (PMID 33979042, 2021). "These include the densities of tumor cells and CSCs, and the concentrations of intracellular signaling molecules (NFκB, Bcl-2, BAX)." (PMID 34669701, 2021). "Western blotting also revealed that ADAMTS9-AS2 overexpression increased the levels of Bax in these tumor cells, whereas such overexpression suppressed Bcl-2 expression and EMT-related protein relative to control cells." (PMID 34178640, 2021). "BCL2 expression was also a significant prognostic indicator in subgroups including tumor size > 2 cm, stage II, ER-positive, HER2-negative, histologic grade 1 or 2, positive lymphovascular invasion, and body mass index ≤ 25 kg/m2." (PMID 34099764, 2021). "Bcl-2 is reported as a possible prognostic marker and factor altering sensitivity of tumor to radiotherapy." (PMID 34178320, 2021).
tumor (continued). "The results show that the levels of BAX and cleaved caspase‐3 have increased and that of Bcl‐2 has decreased in tumours of the gracillin‐treated mice." (PMID 33259114, 2021). "Receptor tyrosine kinase-like orphan receptor 1 (ROR1) is an oncofetal protein that is emerging as a therapeutic target and is co-expressed with BCL2 in multiple tumor types due to microRNA coregulation." (PMID 34088900, 2021). "Oral administration of CK-3 also inhibited the expression of Ki67, N-cadherin, Viemntin, Survivin, cIAP-1, cIAP-2 or BCL-2 and enhanced the expression of E-cadherin in tumor tissues formed by BEL7402 cells in a dose-dependent manner." (PMID 34395292, 2021). "We found that the tumor volume and quality of sh-LINC01087#1 group were markedly inhibited, the miR-384 expression in tumor tissues increased markedly, while the Bcl-2 expression was obviously inhibited." (PMID 34459789, 2021). "In vivo, the inhibitory effect was manifested as apigenin halting the tumorigenicity of Huh7 cells in nude mice by decreasing the tumor volume, weight and increasing apoptosis, and impacting the expression of Bax, Bcl-2, and Ki-67." (PMID 33959508, 2021). "Combination studies disclosed that concomitant administration of Bcl2 inhibitors can sensitize the tumor cells and induce apoptosis." (PMID 34970530, 2021). "Bcl-2, as a complete mitochondrial outer membrane protein, can prevent the apoptosis of tumor cells and has a negative regulatory relationship with Bax." (PMID 34459789, 2021). "Our in vitro functional assays, such as the cell cycle analysis and low BCL2 expression in Plexin-B3 knockdown cells, explain our in vivo observation of a lower tumor burden with less Ki-67-positive cells in mice injected with Plexin-B3 knockdown cells." (PMID 33669221, 2021). "Many studies have shown that Bcl-2 protein is overexpressed in many malignant drug-resistant tumor cells, as the protector of tumor cells against chemotherapy and the overexpression of Bcl-2 confer the pro-oncogenic function through apoptosis inhibition." (PMID 33924348, 2021). "Bcl-2 family proteins, such as Bcl-2, Bcl-w and clAP-2 combine with tumor suppressors to promote apoptosis." (PMID 34838013, 2021). "It has been proposed that therapeutic resistance of GB is due to an up-regulation of anti-apoptotic proteins such as Bcl2 and a downregulation of pro-apoptotic proteins, leading to activation of oncogenes that promote tumor cell survival." (PMID 34298658, 2021). "In DLBCL patients, the presence of miR-21 is suggested to contribute to increased cellular viability and escape apoptotic in tumor cells by targeting BCL2 and PTEN in apoptotic and cell proliferation pathways." (PMID 34679437, 2021). "There are different studies revealing different levels of significance of bcl-2 expression when analyzed in context of grade of tumor from non significant to highly significant." (PMID 34178320, 2021). "Consistently, the MRD monitoring by BCL2‐TLA in a FL patient was able to describe the persistently high tumor burden in a primary refractory patient, tracing a chemo‐resistant clone." (PMID 33742718, 2021).